RPS23P1 (ribosomal protein S23 pseudogene 1)
Synonyms: RPS23RG1; RPS23_3_930
Gene: Processed pseudogene on chromosome 8 (97,865,054 to 97,865,485, forward strand). Ensembl gene ENSG00000243504.
Diseases named in the same sentence as RPS23P1 in open-access papers:
RPS23P1 is named in the same sentence as 5 diseases in open-access papers, as found by Europe PMC text mining. Sharing a sentence is not in itself a finding about the gene and the disease.
RPS23P1 shares sentences with these, for which no sentence is quoted: Alzheimer disease (3 papers); cognitive deficits (2); autism (1); neuroblastoma (1); Parkinson disease (1).